SPATA7 (spermatogenesis associated 7)
Description:
Involved in the maintenance of both rod and cone photoreceptor cells (By similarity). It is required for recruitment and proper localization of RPGRIP1 to the photoreceptor connecting cilium (CC), as well as photoreceptor-specific localization of proximal CC proteins at the distal CC (By similarity). Maintenance of protein localization at the photoreceptor-specific distal CC is essential for normal microtubule stability and to prevent photoreceptor degeneration (By similarity).
Synonyms: HSD3; HEL-S-296; HSD-3.1; LCA3; RP94
Tractability: PROTAC: ubiquitination databases record sites on it.
Gene: Protein-coding gene on chromosome 14 (88,384,924 to 88,470,350, forward strand). Ensembl gene ENSG00000042317.
Subcellular location: Cytoplasm, cytoskeleton, cilium axoneme; Cytoplasm, cytoskeleton, cilium basal body; Cytoplasm, cytoskeleton; Cell projection, cilium, photoreceptor outer segment
Subcellular location (Human Protein Atlas): Mid piece; Primary cilium transition zone; Vesicles
Gene Ontology:
Molecular function: protein binding
Biological process: microtubule cytoskeleton organization; photoreceptor cell maintenance; protein localization to photoreceptor connecting cilium; protein localization to photoreceptor outer segment
Cellular component: axoneme; ciliary basal body; ciliary transition zone; microtubule cytoskeleton; sperm midpiece; photoreceptor connecting cilium; photoreceptor distal connecting cilium; rod photoreceptor outer segment; cytoskeleton; photoreceptor outer segment
Genetic constraint (gnomAD): Loss-of-function variants: 27 observed, 30.53 expected, observed/expected ratio (o/e) 0.88, 90% interval 0.65 to 1.22. The upper end of that interval is the gene's LOEUF score, 1.22, which puts it in group 5 of 6, group 1 being the genes least tolerant of losing a copy. Missense variants: 555 observed, 584.64 expected, observed/expected ratio (o/e) 0.95, 90% interval 0.88 to 1.02. Synonymous variants: 189 observed, 213.26 expected, observed/expected ratio (o/e) 0.89, 90% interval 0.79 to 1.
Gene-disease validity (ClinGen):
ClinGen rates the evidence that SPATA7 causes each of these diseases.
inherited retinal dystrophy (autosomal recessive): Definitive. An instance of retinal degeneration that is caused by an inherited modification of the individual's genome.
Homologues: Orthologues: chimpanzee SPATA7 (98% identical), macaque SPATA7 (92% identical), dog SPATA7 (79% identical), pig SPATA7 (76% identical), rabbit SPATA7 (70% identical), guinea pig SPATA7 (69% identical), mouse Spata7 (67% identical), rat Spata7 (66% identical), tropical clawed frog spata7 (30% identical), zebrafish spata7 (13% identical).
Diseases named in the same sentence as SPATA7 in open-access papers:
SPATA7 is named in the same sentence as 18 diseases in open-access papers, as found by Europe PMC text mining. Sharing a sentence is not in itself a finding about the gene and the disease. The quoted sentences say what the papers report.
Leber congenital amaurosis (5 papers, 2011 to 2025). Leber congenital amaurosis (LCA) is a retinal dystrophy defined by blindness and responses to electrophysiological stimulation (Ganzfeld electroretinogram (ERG)) below threshold, associated with severe visual impairment within the first year of life. "SPATA7 mutations cause the severe early-onset retinopathy Leber congenital amaurosis (LCA, type 3) and juvenile RP." (PMID 26093275, 2015). "Wang first identified variants in SPATA7 associated with Leber Congenital Amaurosis (LCA)." (PMID 41325489, 2025).
Ciliopathies (4 papers, 2015 to 2021). "We identified 10 genes (STK38L, TUBB2A/B, CCNO, ARL13B, RFX2, RAB23, TUBA1C, CEP170B, and SPATA7) that are established or candidate ciliopathy genes." (PMID 34485842, 2021). "This high-confidence list includes many established ciliopathy genes such as TTC26, CEP83, IFT88, and SPATA7, as well as 14 of 25 known JS causative genes." (PMID 26026149, 2015). "NEK1 interacts with other ciliopathy proteins C21orf2 and SPATA7, suggesting that other ciliopathies could likewise be treated with CDK inhibitors." (PMID 30915099, 2019).
retinitis pigmentosa (4 papers, 2014 to 2025). Retinitis pigmentosa (RP) is an inherited retinal dystrophy leading to progressive loss of the photoreceptors and retinal pigment epithelium and resulting in blindness usually after several decades. "Loss-of-function variants in SPATA7 encoding spermatogenesis-associated protein 7 are responsible for human Leber Congenital Amaurosis, and Retinitis Pigmentosa." (PMID 41325489, 2025). "For example, AD, PD, and MND were all associated with SNPs in LAMA2, PTPN12, and SPATA7, which are implicated in muscular dystrophy, colon cancer, and retinitis pigmentosa, respectively." (PMID 35711735, 2022). "Two of the genes (TTC8 and SPATA7) have been associated with Retinitis Pigmentosa (RP) in humans." (PMID 26401321, 2014).
retinal ciliopathy (3 papers, 2017 to 2025). "Previous studies have shown that CFAP410 is a component of a retinal ciliopathy-associated protein complex containing both NEK1 and SPATA7." (PMID 40018707, 2025). "Previous immunofluorescence studies showed that CFAP410 co-localizes with both the serine/threonine kinase NEK1 and a retinal ciliopathy protein called SPATA7 at the basal body in hTERT-RPE1 cells." (PMID 39255848, 2024). "Other studies also showed that CFAP410 is a component of a retinal ciliopathy-associated protein complex containing both NEK1 and SPATA7." (PMID 39255848, 2024).
retinal disease (3 papers, 2022 to 2025). "SPATA7, an early onset LCA3 retinal disease gene, encodes a putative scaffold protein that is essential for the proper assembly of the connecting cilium (CC) complex in photoreceptors." (PMID 35368022, 2022). "As the [SPATA7/PTPN21]DEL variant deleted coding regions of two genes, one linked to retinal disease, we considered it a very likely putative causative variant." (PMID 41325489, 2025). "While the role of SPATA7 for retinal disease has been established in human patients and genetically engineered mice, the role of PTPN21 in the retina is unclear even though it is expressed in rod and cone photoreceptors." (PMID 41325489, 2025).
cone-rod dystrophy (2 papers, 2024 to 2025). Inherited retinal dystrophies that belong to the group of pigmentary retinopathies. "We posit that SPATA7 deficiency is the main cause of the condition, and propose this disease as a model for the SPATA7-related form of cone-rod dystrophy in humans." (PMID 41325489, 2025). "We propose this canine model for the SPATA7-related form of cone-rod dystrophy in humans." (PMID 41325489, 2025).
Bardet-Biedl syndrome (1 paper, 2014). A ciliopathy with multisystem involvement. "Two genes in the region have previously been associated with inherited retinopathies in humans; Spermatogenesis associated protein 7 (SPATA7) has been associated with juvenile RP and LCA, and tetratricopeptide repeat domain 8 (TTC8) with RP as well as Bardet-Biedl Syndrome (BBS)." (PMID 26401321, 2014).
chronic kidney disease (1 paper, 2022). Impairment of the renal function secondary to chronic kidney damage persisting for three or more months. "Five variants associated also with chronic kidney disease progression mapped to genes with functional in-silico evidence (UMOD, SPATA7, GALNTL5, TPPP)." (PMID 35716955, 2022).
Infertility (1 paper, 2025). "For example, alterations in genes such as SPATA7, DNAH1, DNAI1, and DNAJB11 have been associated with MMAF-related infertility." (PMID 40410177, 2025).
schizophrenia (1 paper, 2018). A major psychotic disorder characterized by abnormalities in the perception or expression of reality. "Some of these genes, such as SPATA7 have been implicated in psychiatric conditions, including schizophrenia." (PMID 30563984, 2018).
retinopathies (2 papers, 2014 to 2025). "In contrast, the causative role of SPATA7 in human retinopathies is well established, as its role in the photoreceptor connecting cilium." (PMID 41325489, 2025).
SPATA7 also shares sentences with these, for which no sentence is quoted: Leber congenital amaurosis 3 (3 papers); Blindness (2); colon cancer (1); early-onset retinal dystrophy (1); muscular dystrophy (1); retinal degeneration (1); Retinal dystrophy (1).